SHH (sonic hedgehog signaling molecule)
Diseases named in the same sentence as SHH in open-access papers (continued):
Sharing a sentence is not in itself a finding about the gene and the disease.
myocardial infarction (3 papers, 2018 to 2024). Gross necrosis of the myocardium, as a result of interruption of the blood supply to the area, as in coronary thrombosis. "Mainly, the sonic hedgehog signaling molecule (SHH) preserves cardiac muscle cells after myocardial infarction (MI) in a peroxide-induced oxidative stress environment." (PMID 38539233, 2024). "Other groups also suggested that strategies increasing the SHH signaling pathway may offer useful tools for improving cardiac dysfunction after myocardial infarction in mice 13-15." (PMID 32226535, 2020).
myopia (3 papers, 2019 to 2025). "SHH signaling pathway plays a critical role in the development of myopia by promoting axial elongation through the activation of matrix metalloproteinases (MMPs)." (PMID 40933557, 2025). "In chicks with experimentally induced myopia, SHH expression is increased in the retina, which suggests its involvement in the retinoscleral feedback that controls postnatal eye growth." (PMID 35749127, 2022). "The SHH pathway should also be considered in families with glaucoma, myopia, and retinal vasculopathy phenotypes." (PMID 35749127, 2022). "The potential to modulate SHH activity presents a promising therapeutic target for managing myopia by controlling the overexpression of MMP-2 and managing the structural changes in the eye that lead to myopia." (PMID 40933557, 2025).
neuroblastoma (3 papers, 2015 to 2024). Neuroblastoma (NB) is the most common solid, extracranial childhood tumor. "In addition, the SHH pathway actively influences neuroblastoma activity." (PMID 39568072, 2024). "In addition, our data showed HIF-1α, SHH and GLI1 expression levels were related to International Neuroblastoma Staging System (INSS) stages (Spearman rho = 0.415, P < 0.0001; Spearman rho = 0.487, P < 0.0001; Spearman rho = 0.347, P = 0.003)." (PMID 25811359, 2015).
oligodendroglioma (3 papers, 2020 to 2023). A well-differentiated (WHO grade II), diffusely infiltrating neuroglial tumor, typically located in the cerebral hemispheres. "We believed that the SHh signaling pathway has been shown to be vital role in promoting malignant progression in vivo and distant relapse during oligodendroglioma evolution." (PMID 37533228, 2023). "The PI3K/AKT and SHh signaling pathways may play an important role in promoting treatment resistance and distant relapse during oligodendroglioma evolution." (PMID 37533228, 2023). "Our findings indicate that the PI3K/AKT and SHh signaling pathways may play important roles in promoting tumor distant relapse and drug resistance during oligodendroglioma progression." (PMID 37533228, 2023).
oral cancer (3 papers, 2017 to 2025). "It is worth noting that several of the functional partners including CTNNB1, SHH, FOXA2, and SOX2 have been reported to be involved in the progression of oral cancer or linked with the stem cell phenotype of oral cancer cells." (PMID 38304730, 2024). "The following sections aim to summarize updated literature on the roles of TRAIL, TGFβ, SHH, Wnt, and miRNAs as potential targets for oral cancer therapy." (PMID 28708091, 2017). "Accordingly, the interactions between TRAIL, Wnt, SHH, TGFβ, and miRNA signaling proteins in oral cancer therapy warrant further investigation." (PMID 28708091, 2017). "In this review, we focus on recent advances in targeting therapies for oral cancer and discuss the gene targets within TRAIL, Wnt, SHH, and TGFβ signaling for oral cancer therapies." (PMID 28708091, 2017). "Therefore, these putative SHH inhibitors warrant further investigation in oral cancer therapy in the future." (PMID 28708091, 2017). "Wnt, SHH, and TGFβ pathway signaling proteins are also suitable targets for oral cancer therapy." (PMID 28708091, 2017). "However, the application of these SHH inhibitors in oral cancer treatment is still rare." (PMID 28708091, 2017). "The PRKD1 E710D hotspot mutation and protein expression of PRKD1 and HH components (SHH, IHH, SMO, and GLI‐1) were detected in PAC regardless of tissue invasion, although HH proteins contributed to the morphogenesis of this rare oral cancer." (PMID 40930949, 2025).
Pallister-Hall syndrome (3 papers, 2009 to 2024). Pallister-Hall syndrome (PHS), a pleiotropic autosomal dominant malformative disorder, is characterized by hypothalamic hamartoma, pituitary dysfunction, bifid epiglottis, polydactyly, and, more rarely, renal abnormalities and genitourinary malformations. "A specific example is Pallister-Hall syndrome (MIM #146510) where genetic alterations of GLI3, a transcriptional effector in the SHH signaling pathway, lead to developmental defects of multiple organ systems including uni- and bilateral CAKUT." (PMID 38213489, 2024).
pancreatic ductal adenocarcinoma (3 papers, 2019 to 2021). An infiltrating adenocarcinoma that arises from the epithelial cells of the pancreas. "The aberrant expression of SHH is correlated with oncogenic Kras, which is highly mutated in pancreatic ductal adenocarcinoma (PDAC)." (PMID 32962123, 2020). "ABCB2 (TAP1) is regarded as the downstream target of SHH signaling and plays an important role in enhancing the drug resistance of pancreatic ductal adenocarcinoma." (PMID 33393862, 2021). "Hypoxia found in pancreatic ductal adenocarcinoma increased the transcription of SHH, SMO and GLI-1 and activated the SHH pathway to promote invasiveness." (PMID 32962123, 2020).
pituitary adenomas (3 papers, 2016 to 2021). "On the other hand, in primary cell cultures established from pituitary adenomas, exogenous SHH increased secretion of GH, prolactin, and ACTH from somatotropinomas, lactotropinomas, and Cushing’s tumors." (PMID 32012988, 2020). "However, although human ACTH, GH or PRL-expressing pituitary adenoma show very high expression of the HH signaling inducer SHH and the HH target gene GLI1, a direct link between Hh signaling (e.g. mutations or pathway overactivation) and tumor formation in the AL has not been confirmed." (PMID 33480359, 2021). "However, this information is of great importance because GLI1 and SHH are highly expressed by GH-, PRL- and ACTH-expressing human pituitary adenoma, which suggests that HH signaling has an impact on pituitary tumor formation." (PMID 33480359, 2021). "The expression of the signaling protein sonic hedgehog (SHH) is downregulated in pituitary adenomas and absent in corticotroph adenomas compared with normal pituitary." (PMID 32012988, 2020).
preeclampsia (3 papers, 2020 to 2024). Preeclampsia is a hypertensive disorder of pregnancy that is characterized by new-onset hypertension with proteinuria presenting after 20 weeks of gestation, and depending on mild or severe forms may initially present with severe headache, visual disturbances, and hyperreflexia. "During preeclampsia, SHH has a direct effect on the oxidative stress mechanism in trophoblast cells." (PMID 37894820, 2023). "A study recently reported the dysregulation of the SHH pathway in preeclampsia placentae samples." (PMID 38932210, 2024).
prostate adenocarcinoma (3 papers, 2015 to 2022). "Likewise, LRP1-mediated internalization of SERPINE2/PN-1 inhibits SHH ligand-dependent signaling in human prostate adenocarcinoma cells, which results in down-regulation of SHH and GLI1 expression." (PMID 25901736, 2015). "Importantly, the immunohistochemical analyses have indicated that the increased expression levels of SHH and GLI-1 frequently occur in prostatic adenocarcinoma tissue specimens relative to non-malignant prostate tissues." (PMID 25682877, 2015).
prostate tumors (3 papers, 2006 to 2013). "Previous studies from our group indicated that 54% of malignant human prostate tumors displayed increased levels of Perlecan, which contributed to increased proliferation and SHH signaling." (PMID 22135748, 2011). "We have demonstrated that Perlecan, a candidate gene for the CAPB locus, is a new component of the SHH pathway in prostate tumors and works independently of androgen signaling." (PMID 16507112, 2006). "SHH and IHH were present in all samples, being either benign prostate tissue, localized or metastatic prostate tumor tissues." (PMID 23880852, 2013).
renal cell carcinoma (3 papers, 2023 to 2025). "In contrast, mRNA analysis of the elements of the Hedgehog signaling pathway, such as SHH, SMO, and GLI1 in tissue from renal cell carcinoma showed higher expression levels than healthy tissue, while an underexpression of PTCH1 was observed and specifically in patients older than 60 years." (PMID 38287479, 2024). "However, a limitation of our study is that we just checked the different expression levels of SHH, PTCH and SMO in different tumour gradings, and then we used analysis data from the GDC TCGA renal cell carcinoma (282 patients) to draw the survival curve." (PMID 37240278, 2023).
skin basal cell carcinoma (3 papers, 2018 to 2023). The most frequently seen skin cancer. "The smoothened (SMO) receptor is an essential component of the Sonic hedgehog (SHH) signalling, which is associated with the development of skin basal cell carcinoma (BCC)." (PMID 29776351, 2018). "In other cilia-related tumors, skin basal cell carcinoma and rhabdomyosarcoma often have primary cilia to mediate the constitutive activation of SHH signaling as a major driver of pathogenesis." (PMID 37006607, 2023).
small cell lung carcinoma (3 papers, 2014 to 2020). Small cell lung cancer (SCLC) is a highly aggressive malignant neoplasm, accounting for 10-15% of lung cancer cases, characterized byrapid growth, and early metastasis. "The high expression of SHH in small cell lung cancer tissues and cell lines has been reported in a previous study." (PMID 25013484, 2014).
solitary median maxillary central incisor syndrome (3 papers, 2021 to 2023). A hereditary autosomal dominant condition characterized primarily by single (unpaired) deciduous and permanent maxillary central incisors and short stature. "The solitary median maxillary central incisor syndrome (SMMCI), a special kind of tooth agenesis in human, is associated with SHH pathway." (PMID 36604408, 2023). "This is consistent with the clinical finding that RME treatment shows no expansion effect on midpalatal sutures in patients with solitary median maxillary central incisor syndrome (SMMCI), which was proven to be caused by a mutation in the SHH gene upstream of Gli1." (PMID 34434241, 2021).
tooth agenesis (3 papers, 2023). A tooth disease characterized by failure to develop one or more missing teeth. "The downregulation of WNT/β-catenin is implicated in both tooth agenesis and microdontia, while the over-activation of WNT/β-catenin and SHH signalling is implicated in supernumerary tooth formation." (PMID 36901686, 2023).
urothelial carcinoma (3 papers, 2019 to 2025). A malignant neoplasm derived from the transitional epithelium of the urinary tract (urinary bladder, ureter, urethra, or renal pelvis). "Support for such a role for SHH signaling comes from studies in urothelial carcinoma cells, in which SHH overexpression after PPARG inhibition resulted in a partial rescue of cell proliferation and migration/invasion." (PMID 40167323, 2025). "n = 3 technical replicates (B) Expression of SHH in benign urothelium (white bar) and two subtypes of invasive urothelial carcinomas (basal, dark grey bars; luminal, light grey bars) from patients." (PMID 31036156, 2019). "Increased methylation of the SHH gene induces the basal subtype of human urothelial carcinoma through decreased activity of Hh/BMP signaling feedback between cancer cells and the tumor stroma." (PMID 31036156, 2019). "Furthermore, SHH-expressing urothelial basal cells were identified as cells of origin for urothelial carcinoma, but SHH expression was ultimately lost in urothelial carcinomas." (PMID 36010600, 2022).
alopecia (2 papers, 2019 to 2025). Hair loss usually from the scalp. "PTCH1 mutations or dysfunction can impair SHH signaling, resulting in feather follicle miniaturization, feather cycle disruption, and contributing to alopecia." (PMID 40872583, 2025). "Our prioritization approach has found 12 potential physiological biomarkers of alopecia connected with other vital proteins including SHH and APCDD1." (PMID 30993080, 2019). "Thus, therapeutic strategies targeting these pathways, particularly enhancing Wnt/β-catenin and SHH signaling while inhibiting AR and BMP4, offer promising directions for treating alopecia." (PMID 40872583, 2025).
amyotrophic lateral sclerosis (2 papers, 2018 to 2021). Amyotrophic lateral sclerosis (ALS) is a neurodegenerative disease characterized by progressive muscular paralysis reflecting degeneration of motor neurons in the primary motor cortex, corticospinal tracts, brainstem and spinal cord. "It has been reported that motor neurons can be generated from iPSCs derived from a patient with amyotrophic lateral sclerosis using an agonist of the SHH signaling pathway and retinoic acid." (PMID 30483389, 2018).
astrocytoma (2 papers, 2009 to 2018). "In accordance with this hypothesis, NUMB levels are higher in astrocytomas and cervical squamous carcinoma cells, and the positive effect of NUMBL over SHH signaling can also promote tumor progression." (PMID 29507685, 2018).
atherosclerosis (2 papers, 2018 to 2019). A disease characterized by the build-up of fatty material and calcium deposition in the arterial wall resulting in partial or complete occlusion of the arterial lumen. "In this study, we investigated HHIPL1, an uncharacterized gene at the chromosome 14q32 CAD locus, and showed that it encodes a secreted SHH regulator that modulates atherosclerosis-relevant smooth muscle cell phenotypes." (PMID 31163988, 2019). "Hypoxia has been demonstrated to activate the SHH pathway to enhances the progress of vascular remodeling in a number of human diseases, including atherosclerosis and pulmonary artery hypertension." (PMID 29379041, 2018).
bladder tumors (2 papers, 2012 to 2019). "We analyzed patient outcomes among a set of 41 muscle-invasive bladder tumors from Seoul National University Hospital that were clustered into two groups, showing low SHH expression (n = 31) or high SHH expression (n = 10)." (PMID 31036156, 2019). "Interestingly, we observed high expression level of SHH in cell line HTB2, which is often used as a model system for non-muscle-invasive bladder tumours." (PMID 22361633, 2012).
brain injury (2 papers, 2020 to 2024). Acute and chronic (see also brain INJURIES, CHRONIC) injuries to the brain, including the cerebral hemispheres, CEREBELLUM, and brain STEM. "Future studies will unravel the intricate interplay between fibrinogen, SHH signaling, and progenitor cell dysfunction at the neurovascular interface, which may guide targeted therapeutic strategies to alleviate developmental brain injury after BBB disruption." (PMID 39042684, 2024).
cardiac ischemia (2 papers, 2017 to 2018). "In the therapeutic application of EPCs +SHH molecules, SHH signaling preserve cardiac function and improve cardiac recovery in the context of myocardial ischemia." (PMID 30301174, 2018).
chronic cholecystitis (2 papers, 2020 to 2025). "It has previously been noted that the expression of SHH is increased in gallbladders with chronic cholecystitis and gallbladder carcinoma of adult patients, yet the role of SHH in pediatric gallbladder disease remains poorly understood." (PMID 40003307, 2025). "SHH expression increased in severe chronic cholecystitis but decreased after the progression to gallbladder cancer." (PMID 31979397, 2020). "Aberrant activation of SHH signaling protein could be found in chronic cholecystitis and gallbladder cancer." (PMID 31979397, 2020).
Cognitive impairment (2 papers, 2015 to 2018). Abnormal cognition is characterized by deficits in thinking, reasoning, or remembering. "A single treatment of newborn trisomic mice with an agonist of the SHH pathway (SAG) normalizes cerebellar morphology and restores some cognitive deficits, suggesting a possible therapeutic application of SAG for treating the cognitive impairments of DS." (PMID 25540129, 2015).
colon adenocarcinoma (2 papers, 2009 to 2024). "As the Hedgehog signaling pathway is also implicated in intestinal development, homeostasis, and colon adenocarcinoma, and IHH is the Hedgehog ligand relevant for the colon adenoma formation, this ligand was included in addition to the most prevalent SHH." (PMID 38731849, 2024). "Furthermore increased expression of SHH mRNA in human colonic adenocarcinomas is known to correlate with downstream increased expression of GLI1 leading to promotion of cell proliferation." (PMID 19706168, 2009).
Currarino syndrome (2 papers, 2015 to 2020). "Gene mutations involved in this condition include SHH, EN2, and HLXB9, which can be responsible for Pallister–Hall syndrome, Currarino syndrome, and Townes–Brocks syndrome, but are very rare." (PMID 33143152, 2020).